CHEK2 (checkpoint kinase 2)
Diseases named in the same sentence as CHEK2 in open-access papers (continued):
Sharing a sentence is not in itself a finding about the gene and the disease.
cancer (continued). "Taken together, this is broadly consistent with the hypothesis that CHEK2 MSVs confer increased, but on average lower, risks of a similar spectrum of cancers to PTVs, with risks being mutation dependent." (PMID 39209703, 2024). "In this investigation, familial relationship-adjusted, Bonferroni-corrected genomic ascertainment of two population-based, exome-sequenced, EHR-linked cohorts was used to quantify risk of cancers arising from pathogenic/likely pathogenic germline variants in CHEK2." (PMID 39371170, 2024). "Germline mutations in BRCA1 and CHEK2 may lead to homologous recombination repair deficiency and cell cycle disorder, eliciting cancer at an early age." (PMID 38509102, 2024). "In some families, CHEK2 variants have been considered to be even more cancer-causing." (PMID 39272813, 2024). "Pathogenic or likely pathogenic (P/LP) variants in CHEK2 are associated with increased cancer risk." (PMID 39594831, 2024). "Combined, this approach can be used to help predict the pathogenicity of CHEK2 variants of uncertain significance that are found in susceptibility screening and could be applied to other cancer risk genes." (PMID 39146382, 2024). "Moreover, recent studies have revealed that three common CHEK2 variants, p.Ile157Thr, p.Ser428Phe, and p.Thr476Met, carry a distinctly lower risk of cancer compared to other CHEK2 P/LPs." (PMID 39594831, 2024). "The CHEK2 gene germline sequence variants are frequently studied in different cancers." (PMID 39125905, 2024). "Last, we investigated the mutated cancer driver genes in cancers from CHEK2-deficient individuals." (PMID 38848470, 2024). "Most of the CHEK2 variants found in individuals, however, have an unknown effect on the function of the Chk2 protein, and therefore an unknown potential role in cancer." (PMID 39146382, 2024). "His cancer is associated with a CHEK2 gene mutation and is HER-2 IHC3+ and KRAS G12D positive." (PMID 39221315, 2024). "In addition, nine cases had seven concurrent variations of CHEK2 with other cancer predisposition genes." (PMID 39594831, 2024). "Of these genes, CHEK2 was the only one associated with cancer risk." (PMID 39003285, 2024). "Background/Objectives: BRCA1, BRCA2, ATM, and CHEK2 are known cancer predisposition genes (CPGs), but tumor risk in patients with simultaneous pathogenic variants (PVs) in CPGs remains largely unknown." (PMID 38929805, 2024). "Specifically, mutations in the CHEK2 gene can result in the loss or impairment of protein function, affecting DNA repair and cell cycle regulation mechanisms, thereby increasing the individual’s risk of developing cancer." (PMID 38242891, 2024). "Interestingly, in contrast to BRCA1/2-related cancers, CHEK2-associated BCs appear to lack the genetic characteristics of homologous recombination DNA repair deficiency." (PMID 38091153, 2024). "Using pedigree information from 609 CHEK2 c.1100delC families, we studied whether families are at risk of other cancers in addition to the breast." (PMID 39384226, 2024). "Over time, as genomic testing evolves and increased long-term follow-up of individuals in pediatric and adult populations with CHEK2 variants occurs, greater knowledge of surveillance and cancer risk may become known." (PMID 36980535, 2023). "Further analysis revealed that our population is enriched for pathogenic variants in ATM, BRCA1, and CDH1 genes and that prevalence of pathogenic variants in the CHEK2 gene is lower in the Slovenian population, when compared to GnomAD non-cancer control population." (PMID 37002323, 2023).
cancer (continued). "As such, increased use of tumor genomic profiling assays in pediatric cancer patients may help elucidate the relevance of CHEK2 variants in these cancers, alone and in combination with other genetic events." (PMID 36980535, 2023). "The association of CHEK2 mutation with metastasis appears paradigmatic but gender dependent: A pan-cancer analysis across >10 different cancer types demonstrated 1.8-fold enrichment for CHEK2 (P = 0.045), but not ATM, mutations in metastatic relative to primary tumors only in women, not in men." (PMID 37390209, 2023). "Therefore, further studies are warranted to evaluate the effectiveness and safety of transient CHEK2 inhibition in animal models with a genetic predisposition to cancer." (PMID 37862420, 2023). "The literature reviewing cancer risk in children with germline CHEK2 variants is limited." (PMID 36980535, 2023). "Further studies taking into consideration the type of mutation, the familial history, and the non-genetic risk factors could refine the degree of risk and interest in CHEK2 in medical practice for renal predisposition to cancer." (PMID 38002934, 2023). "In the setting of paired tumor/normal sequencing inclusive of broad cancer-associated gene content and allowing for comprehensive analysis of the CHEK2 gene, variant classification may improve, further delineating which CHEK2 variants may impact cancer risk." (PMID 36980535, 2023). "Therefore, additional investigations are required to explore the BPs and potential mechanisms underlying the action of CHEK2 in the occurrence and progression of cancer." (PMID 38081888, 2023). "This, in conjunction with the variable penetrance of CHEK2 variants, suggests that for many families, the presence of a CHEK2 variant may be more informative in terms of recommended cancer surveillance than family history alone." (PMID 36980535, 2023). "Pathogenic variants in CHEK2 contribute to a moderately increased risk of breast and other cancers." (PMID 35885426, 2022). "Our findings further support the relevance of this deleterious mutation in the increased risk of various cancer types, and opens a new avenue that can be exploited for future development of CHEK2-targeted preventive and therapeutic interventions directed at AGCTs." (PMID 35267514, 2022). "CHEK2, a tumor suppressor gene encoding a protein that prevents entry into the cell cycle in response to DNA damage, has been described as a risk gene for multiple cancer types." (PMID 35174967, 2022). "It has been reported that alterations in the cell cycle checkpoint kinase, CHEK2, might be associated with increased cancer risks in LFS/LFL families." (PMID 36387164, 2022). "There is an urgent and currently unmet need to provide robust information that can inform risk management strategies for carriers of pathogenic variants in intermediate risk genes such as ATM and CHEK2, as these genes are now routinely included on gene panels for cancer predisposition." (PMID 35365198, 2022). "CHEK2 germline pathogenic variants have been associated with a lifetime risk of developing breast cancer of 37% and also to an increased risk of developing other kinds of cancer." (PMID 35456488, 2022). "CHEK2 is a moderate penetrant gene that conveys susceptibility to multiple cancers including CRC." (PMID 35128723, 2022). "Consequently, CHEK2 germline mutations have already been associated with increased occurrence of a specific somatic mutation in a cancer-relevant gene." (PMID 35267514, 2022). "However, a challenging aspect of personalized counseling for BRCA1/2 as well as CHEK2 pathogenic variants is the relatively large range of cancer risk." (PMID 33507482, 2021). "Moreover, we identified four different prioritized VUSs in CHEK2 in five additional cases of our cohort for which we suggest a role in cancer predisposition." (PMID 33840814, 2021).
cancer (continued). "To summarize, CHEK2 is a multisite cancer gene that increases the risk of several cancers." (PMID 32570972, 2020). "Interestingly, the prevalence of germline CHEK2 mutations in cancer patients outnumbers that in CHEK1 by the order of magnitude." (PMID 33322746, 2020). "Likewise, several other genes that were initially implicated as high-risk genes in cancers other than PrCa, such as CHEK2 and BRIP1, have subsequently been shown to increase the risk of PrCa as well." (PMID 32183364, 2020). "Thus, our understanding of CHEK2′s contribution to cancer predisposition is incomplete as founder mutations vary among different ethnics and non-founder alterations account for over 25% of CHEK2 pathogenic variants." (PMID 33322746, 2020). "The existence of a core haplotype shared among all carriers of the variant, independently of the cancer type, matching the conserved region previously identified in the high-density SNP analysis, strongly corroborates a founder effect in the CHEK2 variant c.349A>G." (PMID 33158149, 2020). "The CHEK2 variant has been reported to increase the risk of different types of cancer 2–3 times." (PMID 32695137, 2020). "Other cancer risk-associated CHEK2 variants have been reported, some of which in ethnically defined groups such as the Ashkenazi Jewish population, suggesting the influence of founder effects underlying CHEK2 mutational spectra." (PMID 33158149, 2020). "Patients presenting CHEK2 mutations present a predisposition to certain cancers." (PMID 32570972, 2020). "Since then, a growing body of evidence has suggested that germline CHEK2 variants deserve interest from the perspective of clinical oncology as their carriers face an increased risk of various cancer types that display some specific clinicopathological characteristics." (PMID 33322746, 2020). "In addition to BC, CHEK2 PV/LPVs have also been associated with other cancers, including prostate, colorectal, and gastric cancers." (PMID 32046255, 2020). "These genes, except CHEK2, encode long proteins (>1500 amino acids) and are expected to contain numerous passenger mutations, complicating the identification of low-prevalence cancer-associated mutations using recurrence-based methods." (PMID 32732999, 2020). "The putative role of CHEK2 mutation has been reported in other cancers." (PMID 29682443, 2018). "The BRIP1 mutation c.847T>C and the CHEK2 mutation c.695G>T were found in one of the 504 cancer cases (each) and the ATM mutations c.1595G>A and c.5750G>A were found in two cases (each) of the 710 healthy controls and in six and three cases, respectively, of the 504 cancer cases." (PMID 29659569, 2018). "Three of the identified mutations showed cosegregation with cancer (CHEK2, ERCC3 and FANCM)." (PMID 28050010, 2017). "In a recent study CHEK2 variants have been found among individuals with various types of cancer, which might be partly due to the high population frequency of the common CHEK2 variants (c.1100delC and p.Ile157Thr)." (PMID 27696107, 2017). "The CHEK2 gene on chromosome 22q12.1 is prone to mutate and produce cancer." (PMID 28680382, 2017). "The fact that the CHEK2 R95* mutation may be associated with resistance to anthracyclines in cancer patients emphasizes its possible clinical importance." (PMID 27708748, 2016). "Consequently, harbouring this CHEK2 mutation can result in inadequate DNA repair and consequently increased risk of developing (and sustaining) genetic hits in several cancer types." (PMID 26538833, 2015).
cancer (continued). "However, given the rarity of CHEK2 variants in the Asian population, further studies and family-based co-segregation analyses are required to determine the cancer risks associated with these variants." (PMID 25629968, 2015). "Thus, aberrant CHEK2 activity is associated with checkpoint defects, inadequate DNA repair, and cancer development." (PMID 26318585, 2015). "Since CHEK2 is known to be a multi-organ cancer susceptibility gene, the mutation may have co-segregated with the disease in this family." (PMID 23806170, 2013). "Other founder mutations in CHEK2 have been associated with an increased risk of cancer." (PMID 21569354, 2011). "CHEK2 has been shown to be a multiorgan cancer susceptibility gene." (PMID 18831734, 2008). "This study is the first reporting an association between CHEK2 mutations and therapy resistance in human cancers and to document mutations in two genes acting direct up/down-stream to each other to cause therapy failure, emphasizing the need to investigate functional cascades in future studies." (PMID 18725978, 2008). "Thus, other cancers may be enriched in individuals with heterozygous CHEK2 variants; eTable 4 in Supplement 1 lists counts of cancer types in control participants and case participants in the all, PTV, and PMV groups." (PMID 41396600, 2025). "Furthermore, BCAC and Cancer Risks Estimates Related to Susceptibility Consortium (CARRIERS), suggested BRCA1, BRCA2, ATM, PALB2, and CHEK2 genes as highly penetrant; both consortiums pinpointed that 10% of BC patients have cancer susceptibility germline mutation." (PMID 38890714, 2024). "Thus, the identification of CHEK2 is important, given its impact on cancer risk management." (PMID 39062660, 2024). "Therefore, the presence of germline variants in the CHEK2 gene disrupting the normal function of this protein could result in an increased predisposition to cancer." (PMID 38139220, 2023). "Moreover, the comprehensive functional classification will foster development of clinical interpretation guidelines for germline CHEK2 variants and will allow exploration of the association of germline functionally impaired missense variants with other cancer types." (PMID 37449874, 2023). "An investigation to observe how common germline mutations are in genes that contribute to cancer susceptibility among patients with advanced renal cell carcinoma revealed that out of 254 patients, 41 (16.1%) had germline mutations, and the most frequent mutations were found in the CHEK2 gene." (PMID 37965453, 2023). "Interestingly, some PVs in CHEK2 seem to confer a higher cancer risk than others." (PMID 35886069, 2022). "Therefore, we analyzed CHEK2 in 150 PrCa patients unselected for age of onset, family history of PrCa or clinical outcome, and the frequency of identified variants was compared to findings in 442 cancer-free men, of Croatian ancestry." (PMID 36360192, 2022). "However, depletion of CHEK2 has been reported to increase sensitivity to PARP inhibitors in preclinical models and PARP inhibitors are in clinical trials in cancers with DNA repair deficiencies, including CHEK2 alterations (NCT03786796, 2019; NCT03012321, 2019; NCT02576444, 2019; NCT02401347)." (PMID 36077638, 2022). "These mutations in CHEK2 may represent a genetic cause of intestinal neoplasia and cancer." (PMID 34549727, 2021). "It has been debated in previous studies whether CHEK2 was a high-penetrance cancer-causative gene." (PMID 27900359, 2016).
cancer (continued). "Furthermore, our qPCR analysis led us to presume CHEK2 copy number variation in human, and molecular diagnostics of the cancer susceptibility gene CHEK2 inside the duplicated region might be hampered by the individual-specific set of duplicons." (PMID 18831734, 2008). "A retrospective case–control study used data on 150,962 women tested with a multigene hereditary cancer panel to evaluate an 86-SNV PRS in BRCA1, BRCA2, CHEK2, ATM, and PALB2 P/LP variant carriers." (PMID 39858629, 2025). "Some other genes, like CHEK2, ATM, PALB2, and BRIP1, show a modest tendency for BC; however, patients with these genes' mutations have 2–3 times the high risk of developing a malignant tumor." (PMID 40755497, 2025). "In self-identified White patients, PGV rates in ATM, BRCA1, BRCA2, CHEK2 and Lynch genes were significantly higher compared to two cancer-free male cohorts." (PMID 40832411, 2025). "Among other cancer susceptibility genes, associations were seen for ATM (p = 0.0013), BRCA1 (p = 0.0015), BARD1 (p = 0.00021), CHEK2 (p = 0.039), RAD51D (p = 0.0065), MSH3 (p = 0.0025)." (PMID 39749474, 2025). "Regucalcin has been shown to suppress the gene expression of cell-cycle-related proteins in proliferating cancer cells, including cdc2, cdk2m, chk2 (checkpoint kinase 2), and p21 mRNAs." (PMID 39858022, 2025). "Of these, 103 patients (8.6% of the total sample) carried germline pathogenic variants in genes that have been definitively linked to an increased risk of PC or other types of cancers (BRCA2, ATM, CHEK2, NBN, BRCA1, PALB2, BRIP1 and BARD1)." (PMID 41465280, 2025). "Approximately 10% of patients with aggressive PC carry germline pathogenic variants in genes with established roles in cancer predisposition (BRCA2, ATM, CHEK2, NBN, BRCA1, PALB2, BRIP1, BARD1)." (PMID 41465280, 2025). "Approximately 11% to 17% of patients with metastatic PCa have been reported to have germline mutations in key hereditary cancer genes, including BRCA2, ATM, CHEK2, BRCA1, RAD51D, or PALB2, which represents a substantial population burden." (PMID 41086012, 2025). "These variants were found in over 45% of the cohort and occurred in genes with known relevance to cancer biology, including CHEK2, RAD54L, NOTCH2, ASXL1, PDGFRA, and KIT." (PMID 40627234, 2025). "Using genomic ascertainment in two population-scale cohorts, this investigation quantified the prevalence, penetrance, cancer phenotype and survival in CHEK2 heterozygotes." (PMID 39371170, 2024). "We next explored the effect of ANM-associated genes on cancer outcomes, replicating previously reported associations with PTVs in BRCA2, CHEK2 and PALB2 and cancer outcomes in male and female subjects." (PMID 39261734, 2024). "CHEK2 is an important cancer gene, but it is hard for counselors or physicians to interpret when they encounter a VUS." (PMID 39594831, 2024). "It is important to note that cancer risks are determined by a combination of multiple factors, including rare gene variants such as those in ATM and CHEK2 studied here, but also lifestyle factors, and commoner genetic variants." (PMID 39209703, 2024).